ENSG00000276685
Gene: Miscellaneous RNA gene on chromosome 8 (46,028,804 to 46,028,892, reverse strand). Ensembl gene ENSG00000276685.
Gene Ontology:
Biological process: chromatin remodeling